MMP9 (matrix metallopeptidase 9)
Diseases named in the same sentence as MMP9 in open-access papers (continued):
Sharing a sentence is not in itself a finding about the gene and the disease.
psoriasis (continued). "Upon quantifying the immunohistochemical reactions, we observed that the protein expression of the enzyme MMP9 was higher in the psoriasis plaque than the skin collected from the Non-affected area 154.69 ± 18.94 ou/μm2 versus 136.16 ± 22.92 ou/μm2 (p = 0.0311)." (PMID 34715781, 2021). "Some studies have shown decreased levels of IL-17A, TNF-α, S100A15, S100A7, S100A9 and IL-6 gene expression in PBMCs after NB-UVB treatment in patients with psoriasis whereas other pro-inflammatory mediators such as sVCAM-1, sICAM-1, sE-selectin, MMP-9, and MPO showed no significant reduction." (PMID 30865695, 2019). "Thus, the degradation of the skin basement membrane was significantly, but not fully, blocked in mmp9-MO-injected psoriasis mutant embryos." (PMID 27240166, 2016). "Patients with psoriasis and NMSC showed statistically significant higher plasma NGAL, MMP-9, and CRP levels compared to patients with psoriasis without skin cancers." (PMID 36293148, 2022). "A significant increase in protein and mRNA expression was observed in both heparanases (HPSE and HPSE2), and higher protein levels of MMP9 and TIMP2 were observed in the psoriasis plaque compared to the non-affected skin." (PMID 34715781, 2021). "Moreover, there was a significant increase in HPSE2, SYND1, MMP9, and TIMP2 in non-affected skin samples from patients with psoriasis than in the control sample (tissue obtained by individuals who do not have psoriasis)." (PMID 34715781, 2021). "HPSE2, SYND1, MMP9, and TIMP2 have higher protein expression in the non-affected skin tissue of patients with psoriasis than control tissues, indicating that increased expression of such molecules possibly occurs in the initial stages of the disease even in the absence of psoriatic plaque." (PMID 34715781, 2021).
Insulin resistance (50 papers, 2010 to 2026). Increased resistance towards insulin, that is, diminished effectiveness of insulin in reducing blood glucose levels. "While MMP9 can promote collagen degradation and angiogenesis, counteracting fibrosis, elevated MMP9 levels in ASAT or plasma have been linked to insulin resistance and cardiovascular disease risk." (PMID 40502786, 2025). "The study also compared data such as serum insulin and control of comorbidities, establishing a direct relationship between weight loss, MMP-9,and improvement in insulin resistance and control of metabolic diseases in previously obese patients." (PMID 39766340, 2024). "MMP-9 activity in skeletal muscle of high-fat fed mice is associated with decreased MMP-9 activity, which is indirectly related to the deposition of muscle collagen, but directly related to skeletal muscle insulin resistance." (PMID 38203642, 2023). "This behaviour exclusive to T2D-EC would be consistent with reports that the presence of insulin resistance is associated with a relative reduction in MMP-9 gene expression in AT." (PMID 35481427, 2022). "Secondly, insulin resistance has been linked to heightened activity of MMPs, especially MMP‐2 and MMP‐9, which break down elastin and collagen in the aortic extracellular matrix, resulting in structural weakening and increased risk of dilation." (PMID 41499559, 2026). "In this study, we examined associations between MMP-2 -1306 C/T (rs243865) and MMP-9 -1562 C/T (rs3918242) single-nucleotide polymorphisms, serum levels of MMP-2, MMP-9 and TIMP-1, and the occurrence of insulin resistance in patients in a Polish cohort." (PMID 41828387, 2026). "Inhibition of FOXO1 activity by AS1842856 in insulin resistance conditions (palmitate + glucose) increased elastin and decreased MMP-9 expression compared to palmitate and glucose alone." (PMID 41049496, 2025). "IL-6 upregulates MMP-2 and MMP-9 expression, linking inflammation to vascular remodeling and insulin resistance." (PMID 41227041, 2025). "Increased collagen deposition in the HF-fed MMP9−/− mice was accompanied by exacerbated cardiac insulin resistance with decreased glucose uptake in heart during an insulin clamp." (PMID 38908792, 2024). "In this study, HFD-enhanced TNF-α, ox-LDL, IL-6, and MMP-9 levels, whereas SG markedly downregulated proinflammatory cytokines and reversed insulin resistance, resulting in vascular protection." (PMID 36982743, 2023). "MMP9 (together with VEGF-A) is upregulated in both subcutaneous and omental adipose tissue from morbidly obese patients, MMP9 expression level in fat tissue positively correlated with the homeostatic model assessment for the insulin resistance index." (PMID 37445827, 2023). "Further ECM components potentially representing targets for insulin resistance are hyaluronan, the dystrophin-dystroglycan complex as well as MMP9." (PMID 32265741, 2020). "MMP9 has been reported to be positively correlated with omental adipocyte insulin resistance and MMP9 was decreased in response to pioglitazone." (PMID 31407623, 2019). "MMP-9 is a key mediator of ECM remodeling, which has emerged as a biomarker of CVD and is also associated with insulin resistance and T2D." (PMID 30302090, 2018). "We only demonstrated that both insulin resistance and an increase in serum MMP-9 and MIF coexist in the group of subjects with family history of T2D." (PMID 30302090, 2018). "Pharmacological and behavioural treatments to reduce insulin resistance have been shown to repress MMP-9 secretion." (PMID 28372564, 2017). "Other study demonstrated that MMP-2 and MMP-9 activity in VSC adipose tissue was decreased in an animal model of early insulin resistance." (PMID 26599360, 2015). "MMP2 and MMP9 are regulated by tissue inhibitors, pro-inflammatory cytokines and other factors such as oxLDL or situations of insulin resistance, where the oxidative stress is increased, and they have both pro- and anti-inflammatory actions." (PMID 22828168, 2012).
Insulin resistance (continued). "IL6, MMP9, and LOX1 have been linked to inflammation, insulin resistance, or arteriosclerosis." (PMID 40498722, 2025). "The observed association between insulin resistance (evaluated via the HOMA-IR and Matsuda Index) and MMP9 levels suggests that insulin resistance may influence vascular remodeling through changes in the extracellular matrix degradation." (PMID 40564951, 2025). "Increased collagen deposition by genetic deletion of matrix metalloproteinase 9 (MMP9) exacerbated cardiac insulin resistance and pirfenidone, a clinically available anti-fibrotic medication which inhibits collagen expression, improved cardiac insulin resistance in obese mice." (PMID 38908792, 2024). "Moreover, MMP9 expression in subcutaneous adipose tissue biopsies was shown to be positively correlated with body mass index and insulin resistance in impaired glucose tolerant subjects." (PMID 37445827, 2023). "Furthermore, AFM, GSN, CFH, HGFAC, MMP2, and MMP9 have been previously associated with NAFLD or NAFLD-related factors such as liver damage, insulin resistance, metabolic syndromes, and extracellular homeostasis." (PMID 38034020, 2023). "Moreover, genetic deletion of mmp9 gene resulting in increased protein expression of Col3 and Col4 in the muscle, exacerbated HF diet-induced insulin resistance in muscle." (PMID 32785142, 2020). "In addition, it suggests that ANGPTL2 produced by adipocytes up-regulates MMP9 and proinflammatory cytokine production in macrophages, thereby promoting adipose tissue inflammation, remodeling, and systemic insulin resistance." (PMID 30228336, 2018). "Among them, MMP-2, MMP-9, and MMP-14 are particularly important due to their links with systemic inflammation, insulin resistance, and vascular complications." (PMID 41227041, 2025). "It is important to note that the effects of MMP-9, IL-6, IL-1, and GDF-15 on muscle atrophy and insulin resistance are complex and intertwined." (PMID 38044678, 2024). "Future research should focus on elucidating the precise molecular mechanisms by which MMP-9, IL-6, IL-1, and GDF-15 derived from macrophages exert their effects on muscle atrophy and insulin resistance." (PMID 38044678, 2024). "The role of MMP9 (and MMP2) in sucrose diet-induced insulin resistance needs to be studied in more detail." (PMID 37445827, 2023). "MMP9 expression in adipose tissue is positively related to HOMA-IR and reduces diet-induced insulin resistance." (PMID 35052852, 2022). "The primary endpoints were morning fasting glucose, insulin resistance and insulin sensitivity (HOMA-IR and QUICKI), and metalloproteinases (MMP-9)." (PMID 34070202, 2021). "Here, the up-regulation of gene expression of MMP9 and its positive correlation with the HOMA index point to the potential relationship between this metalloproteinase and insulin resistance development in morbidly obese subjects." (PMID 22471305, 2012). "Of note, in a mouse model of sucrose diet-induced insulin resistance, there was reduced AT expression and activity of MMP9 (and MMP2), with no change in MMP circulating levels nor in PPARγ expression." (PMID 37445827, 2023). "In addition, MMP9, TIMP1, SPP1 and POSTN were shown to play a role in regulating fat metabolism and insulin resistance." (PMID 35966072, 2022). "Also, MMP9, ELANE, NOTCH1, with fewer connected targets, have all been proven to have important regulatory effects in reducing liver lipid accumulation, inflammatory responses, fibrosis, and improving insulin resistance." (PMID 36451177, 2022). "Interestingly, the genetic depletion of MMP9 did not induce insulin resistance in lean mice despite resulting in an increase of collagen IV." (PMID 32265741, 2020).
acute coronary syndrome (49 papers, 2007 to 2026). Signs and symptoms related to acute ischemia of the myocardium secondary to coronary artery disease. "MiRNA126, miRNA21, and both MMP1 and MMP9 are associated with LV and arterial function parameters in patients with acute coronary syndrome." (PMID 39194717, 2024). "Both MMP-2 and MMP-9 are associated with plaque vulnerability and cap rupture, predisposing to acute coronary syndrome." (PMID 36996033, 2023). "In multiple other conditions linked to an activated inflammatory response, such as acute coronary syndrome, chronic urticaria, or pancreatitis, correlations exist between high MMP-9 levels and C-reactive protein (CRP)." (PMID 29929486, 2018). "The previous study also revealed that MMP-9 rs3918242 polymorphism was associated with the susceptibility to acute coronary syndrome (ACS) in the Uygur population of China." (PMID 28390432, 2017). "More specifically, the deregulation of MMP-9 expression has been associated with tumor invasiveness, atherosclerotic plaque rupture in animals with advanced lesions, and acute coronary syndrome in humans." (PMID 27119082, 2016). "In cross-sectional studies, transient elevations of MMP-8 or MMP-9 have been associated mainly with acute coronary syndrome." (PMID 21559401, 2011). "Elevated levels of MMP-9 may be linked to plaque rupture and a fatal acute coronary syndrome (ACS) event, especially if this co-occurs with low TIMP-1 levels, which play a role of natural MMP inhibitor." (PMID 40002748, 2025). "Because MMPs participate in rupture of atherosclerotic plaques, we decided to check whether chronically elevated plasma glucose increases the expression and release of MMP-2 and MMP-9, hence accelerating the risk for acute coronary syndromes." (PMID 28770228, 2017). "In patients with acute coronary syndrome, elevated plasma levels of MMP-9 and TIMP-1 indicate ongoing plaque rupture and an increased risk of subsequent cardiovascular events." (PMID 39200884, 2024). "A previous cross-sectional study showed that MMP-9 levels were significantly higher in patients with acute coronary syndrome than in those with stable angina." (PMID 37085769, 2023). "According to previous studies, plasma MMPs levels, particularly MMP‐9, are higher in subjects with acute coronary syndromes (ACS) and contributed to the molecular process of plaque destabilization." (PMID 33381894, 2021). "Serum expression levels of miR-21-5p have been found to correlate positively with serum activity of MMP-9 in acute coronary syndrome." (PMID 31555200, 2019). "The involvement of MMP-9 in the early hypertensive remodeling has been demonstrated while MMP-9 has been suggested as a biomarker for acute coronary syndrome." (PMID 26692905, 2015). "An increase in circulating MMP-9 contributes to acute coronary syndrome by destabilizing the protective fibrous caps of plaques." (PMID 25897968, 2015). "In conclusions, serum MMP-9 level in acute coronary syndrome was significantly higher in STEMI than that in NSTEACS, whereas MMP-9 (-1562C>T) polymorphism has a trend to be higher in STEMI than that in NSTEACS." (PMID 28348691, 2012). "Overexpression of MMP-9 in the human vulnerable plaques indicates the crucial role of MMP-9 in patients with acute coronary syndrome." (PMID 22716287, 2012). "Other studies have found correlations between plasma MMP-9 levels and symptom severity in patients with acute coronary syndrome, suggesting that MMP-9 could be used as a biomarker for disease progression and patient stratification." (PMID 41245602, 2025). "Thus, it has been suggested that MMP9 is a marker of carotid plaque instability or plaque rupture and a predictor of adverse clinical outcome in patients with acute coronary syndrome." (PMID 38660518, 2024).
acute coronary syndrome (continued). "Disturbed equilibrium of the metalloproteinase/tissue inhibitors system, destabilization of atherosclerotic plaque, and acute coronary syndrome (ACS) in patients are caused by increased expression of MMP-2 and MMP-9 metalloproteinases and their tissue inhibitor (TIMP-2)." (PMID 32486345, 2020). "It was shown that serum MMP-9 and the MMP-9/TIMP-1 molar ratio may be valuable in acute coronary syndrome (ACS) diagnosis and prognosis." (PMID 32486345, 2020). "Soluble lectin-like oxidized low-density lipoprotein receptor-1 (sLOX-1), neutrophil gelatinase-associated lipocalin (NGAL), and matrix metalloproteinase-9 (MMP-9) are inflammatory biomarkers involved in plaque destabilization resulting in acute coronary syndrome (ACS)." (PMID 33214686, 2020). "Clinical research showed that serum MMP-9 levels could be an early marker of plaque rupture contributing to acute coronary syndrome." (PMID 32382308, 2020). "Both MMP-9 and MMP-2 were shown to be released from platelets into coronary circulation during acute coronary syndrome, showing the potential association of MMPs and the development of acute coronary syndrome." (PMID 28770228, 2017). "Our study provided two finding, firstly, high serum MMP-9 level measured in the early time of acute coronary syndrome was significantly elevated in patients with STEMI and secondly, MMP-9 (-1562C>T) polymorphism associated with high serum MMP-9 level in patients with STEMI." (PMID 28348691, 2012). "MMP-9 expression is increased in inflammatory, malignant, and degenerative diseases, particularly in acute coronary syndrome in humans, where circulating MMP-9 levels are increased, suggesting that inhibition of MMP-9 activity might have a therapeutic potential." (PMID 27119082, 2016). "The results demonstrated an increase in plasma levels of MMP-9 and TIMP-1 during acute coronary syndromes." (PMID 38254696, 2024). "Increased plasma MMP-9 and TIMP-1 levels have been demonstrated in the coronary circulation in patients with acute coronary syndrome (ACS), which suggests active process of plaque rupture and future risk of cardiovascular events." (PMID 32486345, 2020). "In acute coronary syndrome, MMP and CRP are correlated, and CRP seems to induce local MMP-9 secretion." (PMID 29929486, 2018). "The balance between MMP-9 and endogenous inhibitor, tissue inhibitors of matrix metalloproteinase 1 (TIMP-1), is important in acute coronary syndrome (ACS)." (PMID 29349668, 2018). "Levels of MMP2, MMP9, TIMP-1 and TIMP-2 are all increased in diabetic patients with dyslipidemia or with acute coronary syndrome." (PMID 25204377, 2014). "The plasma levels of MMP8 and MMP9 have also been shown to increase in AAD compared to healthy controls and to selected patients with acute coronary syndromes." (PMID 23442769, 2013). "Laura found that MMP-9 can promote the transformation of plaque from stable to vulnerable state, increase plaque instability, and MMP-9 has certain value for the prediction, diagnosis and prognosis of acute coronary syndrome." (PMID 33003997, 2020). "In concordance, although the source of MMP-9 cannot be identified when measuring circulating levels, it has been shown repeatedly that levels of circulating MMP-9 are elevated in patients with CHD, in particular those with acute coronary syndrome." (PMID 26389803, 2015). "It has been observed that ox-LDLs upregulate MMP-9 expression and reduce TIMP-1 expression in monocyte-derived macrophages and that MDA, which is included in TBARS, is correlated with the MMP-9 activity in subjects with acute coronary syndrome." (PMID 25114377, 2014). "The aim of this study was to investigate the correlation between the severity of coronary artery lesions in patients with acute coronary syndromes (ACS) and levels of estrogen, high-sensitivity C-reactive protein (hs-CRP) and matrix metalloproteinase-9 (MMP-9)." (PMID 24940407, 2014).
acute coronary syndrome (continued). "The analysis of human coronary lesions has revealed active synthesis of MMP-9 by macrophages and smooth muscle cells (SMCs) in plaques of patients with acute coronary syndromes but not in those with stable angina." (PMID 23365489, 2013). "Increased peripheral blood MMP-2 and MMP-9 in acute coronary syndrome (ACS) may be useful as noninvasive tests for detection of plaque vulnerability." (PMID 32486345, 2020).